CEP131 (centrosomal protein 131)
Diseases named in the same sentence as CEP131 in open-access papers (continued):
Sharing a sentence is not in itself a finding about the gene and the disease.
tumor (12 papers, 2014 to 2025). "Recent work on AZI1 (CEP131) has implicated its role in cilia formation, genome stability, and tumor formation." (PMID 24550735, 2014). "EGR1, OSBPL8 (encoded by the gene KIAA1451), FAM171A2, FGD6, and CEP131 showed particularly high or largely exclusive staining in stromal cells, supporting the notion that indeed the expression profile of CAFs drives tumor classification in our random forest model." (PMID 31505876, 2019). "ARID3A promotes tumor growth by interacting with CEP131 to promote the expression of stem cell-like genes." (PMID 39590360, 2024). "Like HCR, CEP131 is also considered to play an important role in maintaining genomic stability and tumor proliferation." (PMID 36280838, 2022). "We therefore propose that Cep131 overexpression provide favorable condition to accelerate tumor progression by moderately increasing centrosome amplification." (PMID 31358734, 2019). "Collectively, these observations suggest a potential role for USP9X-promoted CEP131 stabilization in breast carcinogenesis." (PMID 28361952, 2017). "CEP131 is a centriolar satellite protein recruited by pericentrin and involved in cilium formation, centrosomal remodeling, and prevention of chromosomal instability in tumor cells." (PMID 31699974, 2019). "Similarly, tumor growth in a breast carcinogenesis model was greatly suppressed by Cep131 depletion." (PMID 31358734, 2019). "Notably, tumour growth in athymic mice receiving tumour transplants with depletion of either USP9X or CEP131 was greatly suppressed." (PMID 28361952, 2017). "Furthermore, Cep131 overexpression accelerated tumor growth between 3 and 4 weeks." (PMID 31358734, 2019). "Analysis of the clinical expression data in the TCGA-LIHC cohort showed that both CEP131 and KDM3A were upregulated in tumour tissues compared to NT tissues." (PMID 36008383, 2022). "In this study, centrosome amplification after Cep131 overexpression in HCC116 cells accelerated tumor formation and growth in nude mice, suggesting a relationship between centrosome amplification and tumor development." (PMID 31358734, 2019). "Besides the previously identified DUB substrates such as CEP131, we found HIF-2α, the critical hypoxia mediator and tumor driver, was among the binding list of USP9X." (PMID 40246814, 2025). "At 5 weeks, tumor volumes and growth in the Cep131-WT expressing group did not noticeably differ from those in the control group, as the tumors reached maximum size." (PMID 31358734, 2019). "The xenograft assay demonstrated that Cep131-depleted cells displayed no tumor formation or growth." (PMID 31358734, 2019).
cancer (11 papers, 2017 to 2025). A tumor composed of atypical neoplastic, often pleomorphic cells that invade other tissues. "Among them, centrosome-associated protein 131 (CEP131), which has been reported to be associated with several types of cancer, was further investigated." (PMID 33014050, 2020). "CEP131 is required for proper centrosome duplication and cilia formation before mitosis begins, suggesting that CEP131 might be associated with cancer development and progression." (PMID 31795161, 2019). "Outside of its structural role in sperm, CEP131 plays a role in centrosome duplication and is up regulated in many cancers." (PMID 40407495, 2025). "Supporting our notion, CEP131 has been recently recognized as an important cancer-related gene in several human malignancies." (PMID 33014050, 2020). "Centrosome protein 131 (Cep131) localizes to both centrosome centriolar satellites and ciliary TZ in mammals and has been demonstrated to be required for ciliogenesis, centriole amplification, genome stability, and cancer." (PMID 38442096, 2024). "Many proteins belong to these families are closely related to cancers, which means ‘CEP72’, ‘CEP131’ and ‘GPR83’ might be predicted as being TC-associated in the future." (PMID 32164526, 2020). "We explored the differential gene expression pattern of Cep131 in normal and cancer samples." (PMID 31358734, 2019). "Thus, Cep131 phosphorylation by Plk4 is critical for centrosome amplification and for cancer progression." (PMID 31358734, 2019). "Moreover, Cep131 overexpression caused excessive STIL recruitment, concurrently accumulating and stabilizing Plk4 and leading to centrosome amplification and cancer development." (PMID 31358734, 2019). "Although Cep131 is not essential to the centriole structure, its dysregulation poses a risk of centrosome amplification and therefore cancer development." (PMID 31358734, 2019). "Both NLP and CEP131 are frequently overexpressed in human cancers." (PMID 29899122, 2018). "Moreover, analysis of differential gene expression using The Cancer Genome Atlas (TCGA) RNASeq data set revealed that overall Cep131 expression level based on average normalized read count is high in several cancers, such as uterine, bladder, lung, kidney, breast, and colon." (PMID 31358734, 2019). "However, a direct link between CEP131 function and cancer promotion remains unclear." (PMID 33014050, 2020). "We believe that the link between CEP131 and USP9X is one of multiple pathways that appear to act in cancer cells." (PMID 28361952, 2017). "Furthermore, Cep131 overexpression contributes to excessive recruitment of STIL to the centriole, which stabilizes Plk4, leading to centrosome amplification and cancer development." (PMID 31358734, 2019). "The CEP131 gene is involved in cell proliferation and migration through the activation of the phosphoinositide 3-kinase (PI3K/Akt) signaling and the SMAD3 gene is a key mediator of the transforming growth factor-β (TGF-β) signaling pathway involved in cancer progression." (PMID 30102725, 2018).
CEP131 also shares sentences with these, for which no sentence is quoted: breast (2 papers); colorectal cancer (2); congenital hydrocephalus (1); glioblastoma (1); infection (1); Infertility (1); lung carcinoma (1); pancreatic cancer (1).